IGHG1 (immunoglobulin heavy constant gamma 1 (G1m marker))
Description:
Constant region of immunoglobulin (Ig) heavy chains. Igs are membrane-bound or secreted glycoproteins produced by B lymphocytes. In the recognition phase of humoral immunity, the membrane-bound Igs serve as receptors, which upon binding to a specific antigen trigger the clonal expansion and differentiation of B lymphocytes into Ig-secreting plasma cells. Secreted Igs known as antibodies mediate the effector phase of humoral immunity by blocking the interaction of infectious antigens with cellular receptors (via the antigen-binding region) and eliciting effector mechanisms that lead to pathogen neutralization (via the constant region). The antigen-binding region is formed by the variable domain of one heavy chain paired with the variable domain of its associated light chain. Each Ig molecule has two antigen-binding sites with remarkable affinity for a particular antigen due to V-(D)-J rearrangement, somatic hypermutations and affinity maturation of the variable domains upon antigen exposure. The constant region defines the Ig isotype that perform distinct sets of effector functions. B cells diversify and rearrange their Ig constant regions through class-switch recombination, a process by which the constant region is switched from one Ig isotype to another, namely from IgM and IgD to IgG, IgA and IgE. The constant region of Ig gamma-1 (IgG1) isotype interacts (via the fragment crystallizable, Fc) with receptors on innate immune cells and the complement system to mediate humoral effector functions, including antibody-dependent cellular cytotoxicity or phagocytosis, complement-dependent cytotoxicity and inflammatory responses.
Tractability: Antibody: its Gene Ontology location is reachable by antibodies, with high confidence; UniProt places it where antibodies can reach, with medium confidence; UniProt predicts a signal peptide or a membrane-spanning region. PROTAC: its protein half-life has been measured.
Gene: Immunoglobulin constant (C) gene on chromosome 14 (105,736,343 to 105,743,071, reverse strand). Ensembl gene ENSG00000211896.
Subcellular location: Secreted (Isoform 1); Cell membrane (Isoform 2)
Pathways (Reactome):
Immune System: Classical antibody-mediated complement activation; FCGR activation; Initial triggering of complement; Interleukin-4 and Interleukin-13 signaling; Regulation of Complement cascade; Regulation of actin dynamics for phagocytic cup formation; Role of phospholipids in phagocytosis
Disease: FCGR3A-mediated IL10 synthesis; FCGR3A-mediated phagocytosis
Gene Ontology:
Molecular function: Fc-gamma receptor I complex binding; protein binding; antigen binding; immunoglobulin receptor binding
Biological process: adaptive immune response; antibody-dependent cellular cytotoxicity; complement-dependent cytotoxicity; antibacterial humoral response; B cell receptor signaling pathway; complement activation, classical pathway
Cellular component: blood microparticle; extracellular exosome; extracellular region; IgG immunoglobulin complex; immunoglobulin complex, circulating; plasma membrane
Homologues: Paralogues in human: IGHG3 (94% identical), IGHG4 (92% identical), IGHG2 (92% identical), IGHE (35% identical), IGHM (32% identical), IGHA1 (29% identical), IGHA2 (28% identical), IGHD (24% identical), IGLL1 (13% identical), IGLL5 (12% identical), IGLC1 (9% identical), IGLC7 (9% identical), and 65 more.
Diseases named in the same sentence as IGHG1 in open-access papers:
IGHG1 is named in the same sentence as 63 diseases in open-access papers, as found by Europe PMC text mining. Sharing a sentence is not in itself a finding about the gene and the disease. The quoted sentences say what the papers report.
prostate carcinoma (14 papers, 2014 to 2025). A carcinoma that arises from epithelial cells of the prostate gland. "In certain cancers, including pancreatic cancer, glioblastoma, and prostate cancer, IGHG1 is associated with immune evasion by cancer cells and immune cell infiltration." (PMID 40566633, 2025). "In prostate cancer, the inhibition of IGHG1 is linked to the suppression of MEK/ERK/c-Myc signaling, leading to reduced malignant growth." (PMID 36883223, 2023). "One manuscript found that Ighg1 was elevated in malignant mesothelioma and Ighg1 has been associated with immune evasion, proliferation and protection from apoptosis in prostate cancer." (PMID 26654940, 2016). "Specifically, the upregulation of IgG containing immunoglobulin heavy constant chain gamma 1 (IGHG1) is strongly associated with various malignancies, including colorectal cancer, gastric cancer, prostate cancer, papillary thyroid carcinoma, leukemia, ovarian cancer, and breast cancer." (PMID 36883223, 2023). "Next, we explored the signaling pathway underlying IGHG1 regulated prostate cancer cell growth." (PMID 31355278, 2019). "IGHG1 promotes tumor development in gastric cancer, breast cancer and prostate cancer via AKT and MEK pathway." (PMID 37503341, 2023). "In prostate cancer research, inhibition of IGHG1 can suppress cell growth and induce cell cycle arrest and ultimate apoptosis." (PMID 33658390, 2021). "In current study, low expression of IGHG1 can inhibit the growth and induce apoptosis of prostate cancer cells." (PMID 33995624, 2021). "Suppression of IGHG1 leaded to growth inhibition and apoptosis induction in human prostate cancer cell." (PMID 34315496, 2021). "Inhibition of IGHG1 suppressed the cell proliferation of prostate cancer and promoted cell apoptosis." (PMID 34553073, 2021). "Silencing IGHG1 expression by siRNA attenuated the colony formation, survival, and cell cycle progression in prostate cancer cells (LNCaP, DU145, and PC3)." (PMID 34226529, 2021). "Inhibition of IGHG1 by genetic knockdown or antibody blocking markedly reduced the growth of prostate cancer cells and induced cell cycle arrest and cell apoptosis." (PMID 31355278, 2019). "By analyzing our immunohistochemical results from prostate cancer samples, we found that the expression of IGHG1 was positively correlated with c-Myc." (PMID 31355278, 2019). "Here, besides siRNA approach, we also applied IGHG1 antibody blocking to further identify the effect of IGHG1 on prostate cancer development." (PMID 31355278, 2019). "We found that IGHG1 was upregulated in clinical prostate cancer tissue from PCa patients and downregulation of IGHG1 reduced the growth and proliferation of PCa cells." (PMID 31355278, 2019). "We have revealed the presence of cytoplasmic and membranous IGHG1 in prostate cancer cell lines (LNCaP, PC3) previously and found that inhibition of IGHG1 by siRNA approach suppressed cell proliferation and induced apoptosis." (PMID 31355278, 2019). "Here, in the current study, we found that IGHG1 was significantly upregulated in prostate cancer tissues." (PMID 31355278, 2019). "To confirm the effect of IGHG1 on prostate cancer cell growth in vivo, we performed a xenograft assay of DU145 cell in athymic nude mice." (PMID 31355278, 2019). "Here, we further supplemented our previous work and we showed that IGHG1 was upregulated in human prostate cancer tissues, comparing with benign hyperplasia samples." (PMID 31355278, 2019). "Our previous reports showed that IgG1 heavy chain (IGHG1) was expressed in LNCaP and PC3 prostate cancer cell lines, and inhibition of IGHG1 suppressed cell viability of PCa cells." (PMID 31355278, 2019). "In order to further determine the role of IGHG1, we firstly searched the Oncomine database for gene expressions in prostate cancer." (PMID 31355278, 2019). "Cell cycle related proteins, such as c-Myc, Cyclin D1, and p21, lied downstream of MEK/ERK pathway to mediate IGHG1 regulated prostate cancer." (PMID 31355278, 2019).
prostate carcinoma (continued). "In conclusion, the data in the current study further confirmed the role of IGHG1 in prostate cancer development." (PMID 31355278, 2019). "In this study, we further determined the effect of IGHG1 and investigated the cellular mechanism of IGHG1 in prostate cancer." (PMID 31355278, 2019). "We previously designed siRNA fragments against IGHG1 and determined that genetic knockdown of IGHG1 suppressed prostate cancer cell growth." (PMID 31355278, 2019). "It is reported that IGHG1 down regulation with siRNA silencing can suppress cell proliferation and apoptosis in prostate cancer cells." (PMID 27336623, 2016). "In addition, inhibition of IGHG1 suppressed prostate cancer growth through inactivation of MEK/ERK pathway, and suppression of MEK activation promoted the accumulation of PPIX in colon cancer cells." (PMID 34553073, 2021). "Moreover, several studies on ovarian cancer, prostate cancer also indicated that IGHG1 promoted tumor migration and metastasis via modulating EMT or MEK/ERK/c-Myc pathway." (PMID 34315496, 2021). "Furthermore, inhibiting IGHG1 expression by siRNA leads to cancer growth inhibition and apoptosis in prostate cancer." (PMID 25318463, 2014). "Furthermore, MEK/ERK/c-Myc pathway lied downstream of IGHG1 in cultured prostate cancer cells." (PMID 31355278, 2019). "Recently, IGHG1 has been reported to facilitate prostate cancer growth via the MEK/ERK/c-Myc pathway, while suppression of IGHG1 expression by siRNA led to growth inhibition and apoptosis induction." (PMID 36752296, 2023). "However, the role of IGHG1 in prostate cancer and the regulatory mechanisms remain largely unknown." (PMID 31355278, 2019). "Human prostate cancer DU145 cells were inoculated into nude mice subcutaneously, and IGHG1 antibody was simultaneously injected into the mice." (PMID 31355278, 2019).
COVID-19 (12 papers, 2020 to 2025). A disease caused by infection with severe acute respiratory syndrome coronavirus 2. "At present, studies have explored the impact of COVID-19 infection on IGHG1 expression, and the research results are consistent with our conclusions, showing that infection with COVID-19 can up-regulate IGHG1 expression." (PMID 40566633, 2025). "Compared to controls, the IGHG1-GM 17 and IGHG3-S variants were associated with an increased risk of critical COVID-19." (PMID 38602517, 2024). "In particular, four of the shared six genes between the McClain and Lee data were immunoglobulin encoding genes: IGHG1, IGHG3, IGHG4, and IGLC2, all of which were consistently upregulated in a COVID-19 specific manner across the datasets." (PMID 35991542, 2022). "Among these down-regulated genes in COVID-19 group, we found IGKC, IGHG1 and IGHV1-2, encoding for immunoglobulin constant and variable chains related to immune response." (PMID 34615949, 2021). "Immunoglobulin-encoding genes were markedly over-expressed in COVID-19 compared to HLTY and INFL, and peaked in OXY1/TUBE EARLY (“hill” pattern, e.g. IGHM, IGHA1, IGHG1, JCHAIN)." (PMID 34135895, 2021). "We show that the proportion of sequences containing the autoreactive AVY & NHS sequence motifs is increased in improving COVID-19 patients compared to stable or deteriorating COVID-19 patients, specifically in the IGHG1 isotype subclass (p-value = 0.013)." (PMID 33384691, 2020). "Comparing isotype subclasses showed a significant increase in the relative usage of IGHG1 in COVID-19 patients —this is the first isotype subclass that is switched to upon activation of IGHM." (PMID 33384691, 2020). "The IGHG1 gene has been confirmed to have higher expression in severe cases of COVID-19." (PMID 40566633, 2025). "Due to the pivotal role of IgG1 in response against SARS-CoV-2, we hypothesized that common functional variants in the IGHG1 gene—either individually or synergistically with IGHG3 and FCGR2A—might modulate the extent of COVID-19 severity." (PMID 38602517, 2024). "Increased levels of S100A8, MKI67, HSPA5, LYZ, CTSD, and IGHG1 were observed in COVID-19 patients." (PMID 39026676, 2024). "However, IGHG1 tended to be highly expressed in the patients with COVID-19." (PMID 36911681, 2023). "The levels of immunity-related proteins (IGHG1, IGLL5, and IGKV4-1) were slightly decreased in the acute phase of COVID-19, confirming that immunity had been suppressed." (PMID 38965561, 2024). "There are five classes of immunoglobulins: IgA, IgD, IgE, IgG, and IgM, and the expression of IGHG1 and IGHG2, the subtype of IgG, tended to be higher in the HD-COVID-19 group, whereas IGHM was higher in the HDs with vaccine group." (PMID 36911681, 2023). "Additional profiling of immune response-related genes highlighted the preferential proximal PAS usage of immunoglobulin genes, such as IGHM, IGHG1, IGHG3, and IGHA2, especially in B cells and plasma cells of COVID-19 samples." (PMID 34376223, 2021). "There was also an increase in the mean CDRH3 length of the BCRs in the COVID-19 patients, that was most pronounced in the IGHA1, IGHA2, and IGHG1 isotype subclasses." (PMID 33384691, 2020).
pancreatic cancer (10 papers, 2013 to 2025). "Previous studies have indicated that IGHG1 demonstrated promotive effects on tumor expansion in murine pancreatic cancer models." (PMID 34315496, 2021). "The mechanism of the increased rate of tumor growth appeared to be related to immunosuppression, as NK cells were less cytotoxic to pancreatic cancer cells that expressed IGHG1." (PMID 24713112, 2014). "IGHG1 expression has been reported to correlate with immune evasion mechanisms, which contribute to the proliferation of human pancreatic cancer." (PMID 25318463, 2014). "Igγ-1 chain C region (IGHG1) was uniquely identified in pancreatic cancer tissue by an LC-MS/MS analysis comparing this tissue with normal pancreatic tissue." (PMID 24713112, 2014). "A cell line expressing IGHG1 on its surface was generated, and when injected into a mouse pancreatic tumor model, resulted in tumors that grew more quickly than in controls, and these mice had shorter survival times." (PMID 24713112, 2014). "Another study showed that in pancreatic cancer, IGHG1 can reduce the cytotoxic activity of NK cells by inhibiting antibody-dependent cellular cytotoxicity function and ultimately producing the effect of contributing to cancer cell proliferation and immune escape." (PMID 40566633, 2025). "High expression of IGHG1 also indicates more immune cell infiltration in glioma and might be responsible for immune evasion in pancreatic carcinoma." (PMID 36752296, 2023). "IGHG1 promotes pancreatic cancer cell proliferation and immune evasion." (PMID 34517344, 2021). "Additionally, the presence of IGHG1 is found in pancreatic cancer cells and might constitute an important element responsible for tumor cell proliferation and immune evasion mechanisms." (PMID 23977302, 2013).
breast carcinoma (7 papers, 2013 to 2025). "Related research indicates that the high expression of IGHG1 is associated with pathological processes such as tumor cell proliferation and migration, facilitating the malignant progression of breast cancer by activating the AKT pathway." (PMID 40179332, 2025). "The upregulation of IGHG1 has also been reported in breast cancer, but its association with cell proliferation and disease progression at the molecular level has not been established." (PMID 36883223, 2023). "The purpose of this study was to validate the association of IGHG1 expression with breast cancer signaling pathways in IGHG1 overexpressed cells." (PMID 36883223, 2023). "Further validation studies are also required to confirm the association of IGHG1 with proliferation, invasion, and angiogenesis in heterogeneous breast cancer tissues that show poor prognosis." (PMID 36883223, 2023). "In this study, we show that IGHG1 is upregulated in breast cancer tissue and is associated with poor prognosis." (PMID 36883223, 2023). "A substantial increase in p-AKT and VEGF proteins was observed in breast cancer cells with elevated IGHG1 expression." (PMID 36883223, 2023). "Through TCGA analysis, qRT-PCR, IHC, and western blot, we have confirmed that IGHG1 expression is upregulated in breast cancer cells." (PMID 36883223, 2023). "We have demonstrated that IGHG1 overexpression promotes cell proliferation, angiogenesis, and metastasis in breast cancer cells, consistent with its role in prostate, gastric, and colorectal cancers." (PMID 36883223, 2023). "An in vivo breast cancer model established by the subcutaneous inoculation of MDA-MB-123 cells as a xenograft in nude mice also demonstrated tumor regression in IGHG1-silenced cells consistent with previous studies in prostate, colorectal, and gastric cancers." (PMID 36883223, 2023). "Overexpression of IGHG1 in breast cancer tissues has also been demonstrated, but an in-depth analysis of its role in disease progression has not been explored." (PMID 36883223, 2023). "Our in vitro and in vivo analyses suggest that the IGHG1 represents a suitable prognostic marker for breast cancer patients." (PMID 36883223, 2023). "Using IGHG1-knockdowns in breast cancer cells, we further show that IGHG1 inhibition suppresses the neoplastic characteristics of breast cancer cell lines." (PMID 36883223, 2023). "One study has demonstrated that high expression of IGHG1 enhanced the breast cancer cell viability, proliferation, and invasion, but reduced cell apoptosis through modulating the AKT pathway." (PMID 36883223, 2023). "A total of three representative breast cancer tissues and adjacent normal tissues were further evaluated for IGHG1 expression using IHC." (PMID 36883223, 2023). "Based on the cutoff value of the median expression of IGHG1 in breast cancer tissues, 70 patients were assigned to the low IGHG1 expression group and 35 to the high expression group." (PMID 36883223, 2023). "We further explore the role of the IGHG1 in breast cancer progression and explore its potential as a future therapeutic candidate." (PMID 36883223, 2023). "We further showed that IGHG1-silencing can suppress the neoplastic characteristics of breast cancer cells in vitro and suppresses tumor growth in nude mice." (PMID 36883223, 2023). "Online GEPIA analysis of TCGA database suggested that IGHG1 levels are significantly higher in breast cancer tissue compared to normal breast tissue." (PMID 36883223, 2023). "qRT-PCR analysis revealed remarkably higher expression of IGHG1 mRNA in breast cancer tissue compared to adjacent normal tissue." (PMID 36883223, 2023). "The expression of IGHG1 mRNA in breast cancer cells nicely agrees with previous studies demonstrating IgG gene transcripts in purified breast cancer cells, breast cancer cell lines and breast cancer tissues." (PMID 23554916, 2013). "Applying various cell markers we demonstrated that the IGHG1 expressing cells were indeed breast cancer cells." (PMID 23554916, 2013).